IL1B (interleukin 1 beta)
Diseases named in the same sentence as IL1B in open-access papers (continued):
Sharing a sentence is not in itself a finding about the gene and the disease.
dengue (62 papers, 2008 to 2026). "Inflammation is a characteristic of murine infection with DENV, and high levels of circulating TNF-α and IL-1β in patients are associated with severe dengue." (PMID 37515098, 2023). "IL-1β and IL-6 are both associated with the severity of dengue fever, promoting the activation of IL-1β and leading to tissue damage and vascular leakage." (PMID 37024713, 2023). "CRP/SAP as well as TNF-α/IL-1β were independently associated with both dengue severity and overall disease manifestation." (PMID 33436908, 2021). "Cytokines including TNF- α, IFN- γ, IL-1β, IL-2, IL-6 and IL-10 have been linked to the pathogenesis of other viral hemorrhagic diseases, such as dengue, and Ebola." (PMID 34793450, 2021). "Endogenous pyrogens (Ex: IL-1β) is induced during dengue virus infection causes fever, a primary symptom of the disease." (PMID 32210961, 2020). "The triggering of severe dengue has been associated with an exacerbated inflammatory process characterized by the production of pro-inflammatory cytokines such as IL-1β/IL-18, which are the product of inflammasome activation." (PMID 30901375, 2019). "Among these factors, at least nitric oxide, RANTES, and IL-1β have been linked to disease severity and vascular instability in dengue-infected patients." (PMID 29761104, 2018). "IL-1β was also found to associate with increase in vascular permeability and is thought to be predominantly released from platelets in patients with acute dengue." (PMID 28284213, 2017). "Of note, increased IL-1β levels associate with thrombocytopenia, increased endothelial permeability, thrombosis, and dysregulated hemostasis in dengue disease." (PMID 25814789, 2015). "Recent studies further demonstrates that serum IL-1β and IL-18 levels correlate with susceptibility to dengue." (PMID 23742038, 2013). "IL-1β was associated with marked thrombocytopenia with OR = 1.058 (CI, 1.012–1.106) in dengue patients." (PMID 18578883, 2008). "Interestingly, sensing of prM-DENV2 triggered the production of TNF-α, IL-1β, and IL-6 cytokines which are usually associated with EC activation and damage during severe dengue." (PMID 36240261, 2022). "Also, 10-fold higher expression of the gene IL1B, which encodes the pro-IL-1β zymogen, has been measured in PBMCs of severe dengue patients compared to DF patients." (PMID 26301593, 2015). "Both interleukins play a key role in dengue immunopathogenesis, and high IL-1β serum levels correlate with the severity of dengue in patients." (PMID 40934228, 2025). "In the literature, IL-1β elevations in dengue patients align with inflammasome activation during infection, and meta-analyses/studies show significant IL-4 and IL-9 increases in acute dengue, consistent with our Th2-associated signals." (PMID 41346606, 2025). "In dengue, primary monocytes are permissive to infection, and infection triggers late activation of caspase-1, IL-1β release and pyroptosis." (PMID 41346606, 2025). "IL-1β treatment restricted Dengue virus infection in vitro in a manner requiring STING, thus demonstrating the functional importance of the IL-1β-mtDNA-cGAS-IRF3 axis." (PMID 39066323, 2024). "Recent studies have reported greater viral replication and IL-10, IL-6, and IL-1β levels in patients with a history of SDD than in individuals with a history of milder dengue disease." (PMID 39583156, 2024). "Previous dengue infection was associated with increased concentrations of IL-17A and IL-1β but decreased concentrations of epidermal growth factor (EGF), and IL-8 compared to dengue-naive individuals." (PMID 37943879, 2023). "Resistin is mainly produced by monocytes, macrophages and other leucocytes and its production is shown to be stimulated by lipopolysaccharide (LPS) and cytokines such as IL-6, TNFα and IL-1β, which are all shown to be elevated during early illness in dengue." (PMID 37676889, 2023).
dengue (continued). "Recent studies have demonstrated important roles of IL-1β in dengue pathogenesis including in tissue injury, vascular permeability and infiltration of inflammatory cells." (PMID 36569864, 2022). "IL-1β is a pro-inflammatory cytokine able to induce iNOS expression in leukocytes and present in dengue patients at high levels." (PMID 36569864, 2022). "Cytokines as IL-1β, IFN-γ, and TNF-α are elevated in severe dengue patients and associate with the degree of thrombocytopenia, hemodynamic instability, and disease severity." (PMID 36569864, 2022). "We then investigated possible factors able to induce platelet iNOS expression and observed higher levels of IL-1β in plasma from patients with dengue, which were correlated with NO production by platelets." (PMID 36569864, 2022). "As the vascular permeability, bleeding, ascitis are the main symptoms of SD patients, we evaluated the levels of IL-1β in dengue patients at the early stage of infection." (PMID 33436908, 2021). "In dengue infection, IL-1β increased in severe dengue, which is associated with thrombocytopenia, tissue injury and vascular leakage, and fibrinolysis." (PMID 34447698, 2021). "Within dengue severity IL-1β, IL-10 (Th1/2), and IP-10 (Th1) have been upregulated in DHF/DSS than DF, and IL-6 (Th1/Th2) and IL-17A (Th17) in DHF than DSS." (PMID 34447698, 2021). "This work studied the status of pentraxin (CRP/SAP) protein, ferritin, TNF-α and IL-1β levels in Dengue patients of different pathophysiological manifestations." (PMID 33436908, 2021). "Higher levels of TNF-α and IL-1β were observed in secondary dengue infections compared to primary dengue cases which was statistically significant (p < 0.0001)." (PMID 33436908, 2021). "Statistically significant increased CRP, SAP, ferritin, TNF-α and IL-1β titres were correlated in patients with severe clinical manifestations as compared to mild disease forms of dengue." (PMID 33436908, 2021). "It is also demonstrated that platelets from dengue-infected patients contribute to increased vascular permeability during infection by the synthesis and release of IL-1β." (PMID 32210961, 2020). "Interaction of platelets isolated from dengue patients with monocytes from healthy individuals lead to the synthesis and secretion of IL-1β, CXCL8, and IL-10 by the monocytes." (PMID 33102253, 2020). "Dengue virus mediated inflammasome initiates the maturation of IL-1β and IL-18, which are critical for dengue pathology and inflammatory response." (PMID 33014899, 2020). "Several evidences have demonstrated the elevated level of IL-1β in serum cytokine and gene expression profiles in severe dengue patients suggesting the contribution of IL-1β in the severity of dengue pathology." (PMID 33014899, 2020). "DENV infection activate the NLRP3 inflammasome, and subsequent activation of caspase-1, and caspase-1 dependent secretion of IL-1β in platelets microparticles from patients with dengue as well as when platelets get exposed to DENV in vitro." (PMID 33014899, 2020). "In corroboration of this logic, previous studies have reported that dengue patients show a decrease in IL-1β levels, which return to baseline levels after the recovery phase." (PMID 30901375, 2019). "In contrast to stored chemokines, platelets from HIV plus dengue coinfected patients secreted IL-1β at levels that were similar to patients infected with DENV only." (PMID 31068600, 2019). "And also, the results reported by other authors were found increased expression of IL-1β in patients with severe dengue, as well as other pro-inflammatory cytokines." (PMID 30901375, 2019). "Serum level of IL-1β was significantly higher in dengue patients than in healthy individuals (24.44 ± 0.68 pg/ml vs. 19.48 ± 0.42 pg/ml, P < 0.0001)." (PMID 31824450, 2019). "We recently reported increased expression of IL-1β in platelets from patients with dengue and in DENV-infected platelets in vitro." (PMID 29761104, 2018).
dengue (continued). "One crucial cytokine seen elevated in severe dengue patients is IL-1β, a potent inflammatory cytokine matured by the inflammasome." (PMID 26301593, 2015). "After LPS-stimulation, monocytes from both dengue and OFIs patients had increased intracellular IL-1β expression, except in DSS patients which showed statistically significant decreased levels especially on Day +1 as compared with other groups (P < 0.05)." (PMID 25722892, 2015). "IL-1β was also detected in platelet MPs from patients with dengue and in MPs from platelets activated by DENV in vitro." (PMID 25814789, 2015). "We recently reported increased expression of IL-1β in platelets from patients with dengue and in platelets exposed to DENV in vitro." (PMID 25814789, 2015). "We used a highly-physiologic system by studying antibody-dependent enhancement of IL-1β in primary human monocytes with anti-dengue human monoclonal antibodies isolated from patients." (PMID 26301593, 2015). "For example, high levels of circulating pro-inflammatory cytokines such as IL-1β or TNF-α in DENV-infected patients correlates with severe dengue fever, compared to patients suffering with mild dengue fever." (PMID 25521078, 2014). "Increased expression of IL-1β in platelets and platelet-derived micro particles is observed in patients with dengue or after platelet exposure to dengue virus in vitro." (PMID 25324778, 2014). "We have previously shown that during dengue there is a significant positive correlation between thrombocytopenia and IL-1β release and that dengue infection leads to assembly of NLRP3 inflammasomes, activation of caspase 1, and caspase 1–dependent IL-1β secretion in dengue." (PMID 36189282, 2022). "Our results demonstrate increased levels of TNF-α and MCP-1/CCL2 in patients that evolved with either mild dengue or warning signs and severe dengue syndromes, while higher levels of IFN-ɣ, RANTES/CCL5 and IL-1β were observed only in plasma from patients presenting warning signs and severe dengue." (PMID 36569864, 2022). "Moreover, IL-1β concentration in plasma positively correlated with NO production in platelets, suggesting a possible participation of IL-1β in platelet nitric oxide synthesis during dengue." (PMID 36569864, 2022). "On the other hand, IL-13 and IL-1β values were lower in acute dengue patients." (PMID 34734091, 2021). "As IL-10 was found to be a key cytokine elevated during early illness during acute dengue, we compared the usefulness of IL-10 in predicting those who are likely to develop DHF, along with other key cytokines such as IL-6, TNFα and IL-1β, which cause vascular leak." (PMID 33199778, 2020). "Another study has tested the hypothesis, whether platelets activation by dengue induce the synthesis and processing of IL-1β, that can be capable of disrupting the endothelial cell barrier function." (PMID 33014899, 2020). "Furthermore, this STING-induced response to IL-1b was essential for the control of dengue virus infection, a flavivirus related to WNV and that this response is linked with protection against WNV neurovirulence in vivo." (PMID 31415679, 2019). "Moreover, a decrease in the expression of the inflammasome-related genes NLRP1, NLRC4, caspase-1, IL-1β and IL-18 was observed, as well as an increase in serum levels of C-reactive protein and IL-10 in dengue patients versus healthy donors." (PMID 30901375, 2019). "In addition to granule-stored chemokines, activated platelets from patients with dengue also release newly synthesized IL-1β33, and IL-1β is also reduced in plasma from coinfected patients." (PMID 31068600, 2019). "In addition, in patients with dengue or after platelet exposure to dengue virus in vitro, increased expression of IL-1β in platelets and platelet-derived microparticles was observed." (PMID 31316518, 2019). "Moreover, the authors demonstrated an increased accumulation of IL-1β in platelets and platelet-derived MPs from dengue patients." (PMID 25999666, 2015).
dengue (continued). "IL-1β is an important proinflammatory cytokine increased during severe dengue." (PMID 25814789, 2015). "Platelet shedding of IL-1β rich MPs also may contribute to enhanced vascular permeability in hemorrhagic viral infections such as dengue." (PMID 25566264, 2014). "However in one study, platelet derived microparticles(PMPs) rich in IL-1b correlated with signs of vascular permeability in patients with dengue, and PMPs were found to induce vascular permeability invitro in an IL1-dependent manner." (PMID 25259615, 2014). "Although the reasons for headache, vomiting and hepatic tenderness in dengue is not clear, it could be due to the high circulating levels of cytokines such as IL-6, TNFα, IL-1β and mast cell products, which are known to be elevated in patients with acute dengue." (PMID 35648794, 2022). "In the case of dengue, the local elevation of GM-CSF triggers inflammatory macrophages, where DENV replicates efficiently and activates the NLPR3 inflammasome through CLEC5A to induce the massive production of IL-1β and IL-18, which are proinflammatory cytokines associated with severe dengue." (PMID 36297236, 2022). "However, the direct contribution of IL-1β to tissue injury in dengue disease remains elusive." (PMID 31824450, 2019). "Importantly, IL-1RA alleviated the damage produced by inflammatory factors, demonstrating that IL-1β may have an important role in the pathogenesis of the dengue disease in a TNF-α-independent manner." (PMID 31824450, 2019). "Higher levels of circulating IL-1β have been detected in the sera of severe dengue patients compared to DF patients." (PMID 26301593, 2015). "In a subsequent analysis comparing mild dengue with the combined DFWS/SD group, significantly higher exosomal levels of IL-1β, IL-5, IL-10, IL-12, IL-13, and TNF-α were observed in the DFWS/SD group (all p < 0.05)." (PMID 41993203, 2026). "More specifically, pro-inflammatory cytokines TNF-α, IL-1β, IL-6, and anti-inflammatory cytokine IL-10 have been shown to be elicited in DHF patients, and in dengue two-hit mouse models." (PMID 37298220, 2023). "Several studies have found that IL-6, IL-17A, IFN-α, IL-1β, IL-10, and TNF-α play different roles in dengue disease, but we didn't know which factor play key roles or even correlated with IL-37b and other factors." (PMID 37024713, 2023). "Altogether, these results indicate that TLR2/TLR6/CD14- mediated sensing of immature dengue particles induces the production of TNF-α and IL-1β by monocytes." (PMID 36240261, 2022). "Around the same time, it was shown that Dengue-induced NLRP3 inflammasome activation increased platelet-mediated endothelium permeability and this was followed by increased expression of IL-1β in vitro and in patient serum." (PMID 36298668, 2022). "Plasma levels of IL-1β, TNF-α and IFN-ɣ were increased in plasma from dengue patients in the present report." (PMID 36569864, 2022). "Then they showed the IL-1β production induced by E III was mediated by NLRP3 and caspase-1 and suggested this was responsible for Dengue-induced pathogenesis." (PMID 36298668, 2022). "We used the KU812 cell line to demonstrate for the first time that anti-dengue antibodies enhanced infectious Zika virus replication in a mast cell model and specifically increased CCL5, CXCL10, and IL-1β, while also impairing granzyme B secretion." (PMID 35862953, 2022). "Among them, a vast panel of increased cytokines and chemokines in severe dengue, such as IFN-γ, GM-CSF, IL-10, CCL4/MIP-1β, IL-1β, CXCL8/IL-8 TNF-α, CXCL10/IP-10, CCL2/MCP-1, and IL-18." (PMID 35631030, 2022). "Our group has previously demonstrated that platelet activation in dengue induces NLRP3 inflammasome activation and increased IL-1β secretion, which contributes to increased endothelial permeability." (PMID 36569864, 2022). "IL-1β increases the vascular permeability, especially in concurrence with TNF-α and IFN-β in many severe dengue profiles." (PMID 33014899, 2020).
dengue (continued). "Spleen Tyrosine Kinase (Syk) augments IL-1β induction during antibody-enhanced dengue virus infection in primary human monocytes, however caspase-1 and NLRP3 are required for the maturation of pro-IL-1β during antibody-dependent enhancement." (PMID 32210961, 2020). "Many different chemokines and cytokines have been shown to be elevated in severe dengue such as IFN-γ, GM-CSF, IL-10, MIP-1β, IL-1β, IL-8 TNFα, IP-10, MCP-1, and IL-18." (PMID 33194836, 2020). "During secondary dengue infection, antibody-dependent enhancement (ADE) has been an anticipated mechanism in explaining dengue hemorrhagic fever (DHF; Guzman and Vazquez, 2010) and studies have observed higher IL-1β level in DHF patients as compared to DF patients." (PMID 33014899, 2020). "The next step was to quantify the serum levels of IL-1β, IL-6, IL-18, IL-10, TNF-α and CRP, as indicators of the inflammatory status in the dengue patients." (PMID 30901375, 2019). "Consistently, dengue plus HIV coinfected patients also presented lower levels of plasma pro-inflammatory cytokines (IFN-γ and IL-1β) and platelet-derived chemokines (RANTES and PF4) when compared to patients infected with DENV only." (PMID 31068600, 2019). "Similar to previous reports, the pro-inflammatory cytokines IL-1β, IFN-γ, TNF-α and MIF were increased in plasma samples from patients with dengue at the acute phase compared to samples obtained after recovery." (PMID 31068600, 2019). "This study is an attempt to build a mathematical model, to address the combined effect of cytokines and immune mediators S1P, IL-1β, TNF-α, PAF and IL-10, and determine the severity of dengue at an early stage." (PMID 28284213, 2017). "We demonstrated that dengue induces NLRP3-inflammasome assembly and caspase-1-dependent IL-1β secretion in platelets." (PMID 25814789, 2015). "Dengue virus infection leads to assembly of NLRP3 inflammasomes, activation of caspase-1 and caspase-1-dependent IL-1β secretion." (PMID 25324778, 2014). "Anti-enolase antibodies induced apoptosis in endothelial cells and production of inflammatory mediators by monocytes and macrophages, including TNF-α, IL-1β and IFN-γ, which are also increased in the plasma of dengue patients." (PMID 25171719, 2014). "We observed that cytokine concentrations of IL-1β, IFN-γ, IL-4, IL-6, IL-7, IL-13 and GM-CSF were significantly increased during severe dengue as compared to mild dengue, while MIP-1β levels are higher in mild dengue." (PMID 18578883, 2008). "Moreover, high serum levels of TNF-α, IL-1β, IL-6, CXCL-8/IL-8, and IL-10 correlated with severity of the disease in dengue patients, showing a preponderant role of NF-kB-dependent inflammatory response in dengue immunopathogenesis." (PMID 40934228, 2025). "Inflammatory cytokines IL-1β and TNF-α are commonly elevated in dengue cases." (PMID 36297236, 2022). "The levels of CRP (p < 0.0001), SAP (p < 0.0001), ferritin (p < 0.0001), TNF-α (p < 0.0001) and IL-1β (p < 0.0001) were high in patients with Severe Dengue as compared to Dengue without warning signs." (PMID 33436908, 2021). "The cytokines IL-1β, CXCL8, and IL-10, released by monocytes in response to interactions with platelets from dengue patients, are frequently observed to be increased in plasma of severe dengue patients." (PMID 33102253, 2020). "In dengue infection, platelet-monocyte aggregation was induced in dengue patients and the aggregate formation could enhanced the production of cytokines and chemokines by monocytes including TNF-α, IL-1b, IL-8, and CCL2/MCP-1." (PMID 30744623, 2019). "Similarly, the percentage of platelets expressing IL-1β evaluated by flow cytometry in a smaller number of patients (9 dengue and 4 HIV + dengue) showed similar levels between dengue infection and HIV + dengue coinfection." (PMID 31068600, 2019). "Dengue-infected monocytes could stimulate cytokines/chemokines production (e.g., TNF-α and IL-1β) which are known to activate endothelial cell." (PMID 25722892, 2015).